EGFR (epidermal growth factor receptor)
Diseases named in the same sentence as EGFR in open-access papers (continued):
Sharing a sentence is not in itself a finding about the gene and the disease.
cancer (continued). "In this platform, the palmitoylation inhibitor 2-bromopalmitic acid (2-BP) was encapsulated in PLGA nanoparticles to enhance the treatment efficacy of afatinib against EGFR-TKIs non-sensitive cancer cells." (PMID 37514008, 2023). "In an effort to identify genes among the hub genes that could potentially contribute to EGFR–TKI resistance and serve as predictors of cancer progression, we conducted DFS analysis for NSCLC patients using the Kaplan–Meier plotter database." (PMID 37816585, 2023). "The results revealed no significant amplification of EGFR gene copy number in RBC DNA of cancer patients compared to healthy subjects and benign nodules." (PMID 36599687, 2023). "Furthermore, a significant correlation has been observed between high EGFR expression and the TNM cancer stage at the time of diagnosis." (PMID 37895912, 2023). "This means that EGFR allosteric inhibitors are not “cancer cell killers” but are, rather, molecules that restore the lost ability of cancer cells to die like normal cells after a limited number of generations." (PMID 37754201, 2023). "Therapeutic approaches targeting RTKs such as vascular endothelial growth factor receptor (VEGFR), epidermal growth factor receptor (EGFR), and platelet-derived growth factor receptor (PDGFR), and TKs, such as c-Src, ABL, JAK, are widely used to treat human cancers." (PMID 36818331, 2023). "Given the consistently negative results for EGFR-targeted therapy in esophago−gastric cancer, except for a biomarker-driven clinical trial, it seems unjustifiable to promote these agents." (PMID 37046849, 2023). "CDKis, e.g., palbociclib, ribociclib, and abemaciclib, inhibit the cell cycle progression of cancer cells in patients with advanced or metastatic hormone receptor (HR)—positive and human epidermal growth factor receptor 2 (EGF-R)—negative cancer." (PMID 36767928, 2023). "Sorafenib-acquired resistance reportedly involves a variety of mechanisms, including multiple-signal pathway crosstalk; abnormal expression of tyrosine kinase receptors, such as PDGFR- β, c-kit, Flt-3, VEGFR and EGFR; epithelial-mesenchymal transition (EMT); and cancer stem-cell differentiation." (PMID 36698167, 2023). "Despite a breadth of preclinical efforts and successful use for other cancer types, EGFR inhibition has not translated into an effective clinical approach for GBM." (PMID 37324218, 2023). "GPER/EGFR/ERK transduction signaling triggers c-Fos and c-Jun expressions, which could induce chromatin-activated protein 1 (AP-1) complex to promote cancer cell migration." (PMID 36741908, 2023). "PI3Kβ inhibition blocks ALK‐inhibition‐induced cytoprotective reactivation of EGFR signaling, enhancing the cytotoxic effect on both epithelial‐ and mesenchymal‐phenotype cancer cells without affecting normal lung epithelial cells." (PMID 36423211, 2023). "Unfortunately, with regard to resistance to third-generation EGFR inhibitors, there were no major breakthroughs in cancer treatment." (PMID 37754201, 2023). "Sentani and colleagues reported that mixed type GC showed a characteristically expression of cancer stem cell-related molecules (CD44, CD133, and ALDH1), receptor tyrosine kinase molecules (EGFR, c-MET, and HER2), and chromosomal instability compared to pure type GC." (PMID 37950183, 2023). "In addition to the typical activation of EP receptors, PGE2 has been shown to promote cancer progression through interaction with carcinogenic signals, including epidermal growth factor (EGF) and its receptor (EGFR)." (PMID 37138287, 2023). "Additionally, RHOV activates EGFR signaling through GRB2, thereby regulating cancer cell migration and promoting metastasis in TNBC." (PMID 37596964, 2023).
cancer (continued). "Notably, this coexpression pattern between AXL and MIG6 was confirmed in cancer cell lines and NSCLC patients, suggesting potential collaboration in regulating EGFR signaling." (PMID 37834326, 2023). "The second explanation could be that GALNT2 initiates O‐glycosylation at the same sites on EGFR and MET, but the glycosyltransferases for further modification of the O‐glycans are differentially expressed in different cancer types." (PMID 36409270, 2023). "Non-small cell lung cancer (NSCLC) has one of the highest CD73 expression signatures among all cancer types and the presence of common oncogenic drivers of NSCLC, such as mutant epidermal growth factor receptor (EGFR) and KRAS, correlate with increased CD73 expression." (PMID 37033953, 2023). "While TGFβ inhibitors are currently not used in the standard-of-care cancer treatment, there are numerous EGFR inhibitors used in cancer care, including the anti-EGFR mAb, cetuximab, which is FDA approved for the management of HNSCC." (PMID 37377902, 2023). "Finally, the molecular docking and core ingredients analysis showed that quercetin was the core ingredient of JQH and bound well with several inflammation-cancer targets, including AKT1, EGFR, HIF1A, and IL6A." (PMID 37964307, 2023). "Afatinib irreversibly binds to epidermal growth factor receptor (EGFR) and Her2 and inhibits tyrosine kinase followed by the activation of the Ras‐MAPK and PI3K‐Akt signaling pathway, which play critical roles in the cancer cell proliferation, migration, and survival." (PMID 36102619, 2023). "Syndecan-4 is an emerging target for cancer treatment, and several cancer therapeutics have been found to downregulate it like trastuzumab (humanized anti-HER2 monoclonal antibody) and panitumumab (human anti-EGFR monoclonal antibody)." (PMID 38106420, 2023). "Indeed, many of these gene dependencies strongly correlate with either a drug-sensitive or a drug-resistant state to inhibitors of EGFR or RTK signaling, albeit varied p values mainly due to different cancer lineages screened." (PMID 36961502, 2023). "Most commonly used small molecular weight drugs for cancer treatments target tyrosine kinases such as EGFR, which are not cancer-specific and so give rise to significant side effects." (PMID 37190286, 2023). "In particular, PGE2 and EGF/EGFR may synergistically promote the growth, invasion, epithelial mesenchymal transition (EMT) and stem cell like phenotype of cancer cells." (PMID 37138287, 2023). "Studies made in recent years have shown that EGFR has pro-survival functions that are independent of its tyrosine kinase activity in cancer cells." (PMID 37446288, 2023). "It has been proven that EGFR can be found in two states in cancer cells: with the capacity to be activated or without this capacity." (PMID 37446288, 2023). "Our results showed that nanotechnologies use to enhance the efficacy of anticancer drugs such as: cisplatin, paclitaxel, cetuximab, EGFR antagonists, MEK1/2 and immune check inhibitors combination could have promising anti-cancer activity." (PMID 37189730, 2023). "Lineage transition from adenocarcinoma (AD) to aggressive neuroendocrine (NE) derivatives is a common type of cancer cell plasticity in androgen deprivation therapy–treated (ADT-treated) prostate AD (ADPC) and epidermal growth factor receptor (EGFR) inhibitor–treated lung AD (LUAD)." (PMID 38099497, 2023). "Possible mechanism is that viral replication may be activated by epidermal growth factor receptor (EGFR)/Ras pathway signaling, cellular TK levels, as well as resistance to type-I interferons (IFNs) of cancer cells." (PMID 37182136, 2023). "SLCO4A1-AS1 exerted a suppressive effect on cancer stemness but not on EGFR TKI/chemotherapeutic agent sensitivity." (PMID 37726723, 2023). "Indeed, we found that the interaction between PRV and EGFR depends on NRP1, as it mediates virus entry into cancer cells via macropinocytosis and lipid raft-dependent endocytosis." (PMID 37891570, 2023).
cancer (continued). "Elevated ERER levels can lead to aberrant activation of the epidermal growth factor receptor (EGFR/ERBB1), and the activated EREG/EGFR pathway further regulates various cellular functions, including cancer cell proliferation, survival, metastasis, and angiogenesis." (PMID 37880277, 2023). "In concordance with this, BRAF-mutant CRC cell lines express higher levels of EGFR than BRAF-mutant melanoma cell lines, which may explain the difference in the efficacy of BRAF inhibitors in the clinical setting among cancer types." (PMID 36900187, 2023). "WWP1 promotes cancer stemness in NSCLC by inducing ubiquitination and stabilization of EGFR." (PMID 38129384, 2023). "PD-L1-upregulated expression on cancer cells occurs via four primary mechanisms: (I) the DNA damage signaling pathway; (II) interferon gamma (IFN-γ) signaling; (III) the cGAS-STING pathway; and (IV) the epidermal growth factor receptor (EGFR) pathway." (PMID 37887283, 2023). "EGFR, the first of four members of the ErbB family, is overexpressed in 40–80% of NSCLC cancers." (PMID 37762316, 2023). "Moreover, using both in vitro and in vivo models, some studies also reported that ionizing radiation (IR) induces activation of EGFR, HER2, HER3, and HER4, and interestingly, silencing of HER3 inhibits the viability of cancer cells after treatment with IR." (PMID 37947595, 2023). "As exemplified by EGFR and RPTOR, these new CDK12/13 target genes function in pathways that are actionable in HGSOC, as clinically approved inhibitors have shown efficacy in other cancer types." (PMID 37202753, 2023). "Moreover, we also detected several biomarkers of cancer proliferation and cell apoptosis such as VEGFA, EGFR and HIF-α, and the anti-apoptotic factor Bcl-2." (PMID 36855119, 2023). "Stabilizing the EGFR on the plasma membrane, NHERF1 increases cell sensitivity to the tyrosine kinase inhibitors that affect EGFR-driven motility and invadopodia-dependent ECM proteolysis in cancer cells." (PMID 37415743, 2023). "The membrane transporter ABCC1 (MRP1), which confers multidrug resistance to cancer cells, was also enriched in the Panc-1 library, along with three other SLC transporters, SLC4A2, SLC30A1, and SLC12A7 (KCC4), plus the epidermal growth factor receptor EGFR and lipid transport protein ESYT2." (PMID 37295717, 2023). "They serve as negative prognostic factors for carcinogenesis and anti-EGFR therapy because intracellular signal interruption leads to uncontrolled cellular proliferation and cancer." (PMID 37835512, 2023). "The activation of STAT3 would also lead to various STAT3-dependent pathways, such as the interleukin-8/STAT3 (IL-8/STAT3) and EGFR/STAT3/SRY-box transcription factor 2 (EGFR/STAT3/SOX2) pathways, which have been shown to play important roles in cancer stemness." (PMID 37760799, 2023). "Although EGFR is considered to be a key therapeutic target in many types of cancers, for reasons that are still unclear, targeting EGFR in OC patients resulted in a very poor response not correlated to EGFR expression." (PMID 37041632, 2023). "Besides genetic factors, a hypoxic environment has been shown to induce overexpression of EGFR in cancer and to upregulate both TGFA and VEGF-A in cancer and ECs." (PMID 37199488, 2023). "For instance, epithelial subtypes CMS2 and CMS3 are more dependent on EGFR than CMS1 and CMS4, which was shown before and further supports earlier clinical observations which suggest that CMS4 cancers do not respond to anti-EGFR therapy." (PMID 36869386, 2023). "It is known that UA may decrease the proliferation of cancer cells and induce apoptosis by suppressing the epidermal growth factor receptor (EGFR)/MAPK pathway, and it also suppresses cancer metastasis via the integrin αVβ5/MMPs pathway." (PMID 37089712, 2023). "When the EGFR gene is hypomethylated in OSCC, it leads to a higher production of EGFR protein, which means that it stimulates the uncontrolled growth and division of cancer cells." (PMID 38067304, 2023).
cancer (continued). "NRP1 and EGFR were highly expressed in most cancer cells, and this suggests that PRV-LAV may have potential utility in personalized cancer therapy among patients with NRP1/EGFR-overexpressing tumors." (PMID 37891570, 2023). "Epidermal growth factor receptor inhibitors (EGFRIs) induced cutaneous toxicity is a common adverse event (AE), although it is not as severe as major cancers, we still need to pay enough attention to them." (PMID 38327269, 2023). "When the EGFR is activated by ligands such as transforming growth factor (TGF) a, protein substrates, such as phospholipase C and phosphatidylinositol-3-kinase, are tyrosine phosphorylated, leading to increased cancer proliferation and survival." (PMID 37508387, 2023). "Currently, monoclonal antibodies like cetuximab and panitumumab are used to target EGFR in certain cancer types, but there is no specific mention of these antibodies being approved for GBPS." (PMID 37635229, 2023). "One possible explanation is that Spike 1 may directly target EGFR while RBD uses other targets at the cancer cell surface including ACE2 resulting in AKT and ERK1/2 phosphorylation independently of EGFR." (PMID 37112680, 2023). "One of the main EGFR pathways is the phosphatidylinositol-3-kinase (PI3K) and its downstream molecule serine/threonine protein kinase B (PKB or Akt) that inhibits the apoptotic effect and, when overactivated, induces cancer development." (PMID 37259433, 2023). "Although EGFR inhibitors have been widely used for the treatment of malignant tumors, they do not influence the activity of PRV oncolytic agents as a novel therapy against EGFR-overexpressing tumors." (PMID 37891570, 2023). "DNAJB11 could regulate epidermal growth factor receptor (EGFR) expression and initiate the subsequent mitogen-activated protein kinase (MAPK) signaling pathway, ultimately promoting cancer." (PMID 37893166, 2023). "The most frequently amplified genes in all cancers are MYC, EGFR and ERBB2 (HER2)." (PMID 37298484, 2023). "After treated with Ro5-3335, a RUNX1-CBFβ interaction inhibitor, the phosphorylation level of EGFR (Tyr1068), STAT3 (Tyr705) and AKT (Ser473, Thr308) were significantly decreased in control cancer cell lines (SKOV3, OVCAR3) and generated the similar pattern that RUNX1 knockdown induced." (PMID 38057816, 2023). "The ErbB RTKs (EGFR, HER2, HER3, and HER4) have been well-studied in cancer." (PMID 37508387, 2023). "Further, EGFR and FASN form a positive feedback loop in cancer cells, which needs to be investigated in Cr(VI)-transformed lung cells as it may provide more mechanistic evidence of the role of FASN in Cr(VI)-transformed cell growth." (PMID 38069382, 2023). "UBC may also interact with epidermal growth factor receptor (EGFR), whose inactivation by tyrosine kinase inhibitors is effective in improving the survival rates and quality of life of many cancer patients." (PMID 37056934, 2023). "In our meta-analysis, we identified six genes with high mutation prevalence in brain metastases, of particular interest for their potential role in brain metastatic process and resistance to first-line anti-cancer drugs: ESR1, ERBB2, EGFR, PTEN, BRCA2 and NOTCH1." (PMID 36980614, 2023). "The reason why cancers expressing/overexpressing wild-type EGFR mutation don’t have a good response to EGFR TKIs is connected to the fact that these types of cancers are not addicted to the EGFR functions for growth and/or survival." (PMID 37446288, 2023).
cancer (continued). "The dysregulation of EREG may contribute to the progression of various cancers including HNSCC and may be a putative mechanism of resistance to EGFR-targeted therapies." (PMID 36899869, 2023). "In addition, palmitoylated EGFR in TKI‐resistant EGFR‐mutant NSCLC cells positively regulates FASN and further promotes cancer cell growth through the Akt pathway." (PMID 37143582, 2023). "In siliconsilicon analysis, we investigated the binding free energy (ΔG) of Neuropilins, an anti-cancer therapy targeting angiogenesis through the inhibition of vascular endothelial growth factor (VEGF), with various signaling pathways including CDK4, EGFR, RAS, BRAF, PI3K, and PTEN." (PMID 37885828, 2023). "lnc-EGFR: lnc-EGFR, which is present in exosomes derived from CRC (CRC) and other carcinomas, could potentially facilitate immune evasion via the EGFR signaling pathway, possibly inducing T cell exhaustion." (PMID 37760852, 2023). "Additionally, THP-1.SIRP-ß2 also potentiated phagocytosis of carcinoma cell lines DLD-1 and OVCAR-3 compared to THP-1.EV upon treatment with EGFR-antibody cetuximab (CTX)." (PMID 38116002, 2023). "By proteomic analysis, mutant KRAS colon cancer-derived EVs were discovered to transport mutant KRAS and other oncogenic proteins such as EGFR, SRC family kinases and integrins, toward neighbor cancer cells with wild-type KRAS, leading to enhanced growth of these neighbor cancer cells." (PMID 35927755, 2022). "•Proteomics for isogenic and cancer-derived models of c-MYC, AKT, BRAF, EGFR, HER2, KRAS, and MEK." (PMID 35594991, 2022). "The epidermal growth factor receptor (EGFR)) is a receptor tyrosine kinase of the ErbB/HER family, that forms homo- and hetero-dimer receptors and modulates cancer cell proliferation, cellular adhesion, motility, apoptosis, progression, and migration by activating signal transduction pathways." (PMID 36412852, 2022). "Depending on cancer characteristics, first-line therapy for advanced CRC is combination chemotherapy plus an anti-epidermal growth factor receptor (EGFR) antibody or anti-vascular endothelial growth factor (VEGF); however, progression-free survival time for most patients is within 9–12 months." (PMID 34716473, 2022). "Given the complex biology of CTCs in a patient with advanced cancer, combining a negative and a positive selection strategy can maintain the recovery rate and purity of isolated CTCs before EGFR testing." (PMID 36142574, 2022). "These enriched pathways including ErbB signaling pathway, EGFR tyrosine kinase inhibitor resistance, viral carcinogenesis, proteasome, and apoptosis, and most of them have proven to be effective therapies against cancer." (PMID 36244991, 2022). "Molecular aberrations that were shared in at least one P/X pair and that were previously recognized to have deleterious effects in human cancers included CHEK2 [K416E; 415S (SNP)], EGFR (158N), ATM (P1054R), STK11 (D194N), PIK3CA (E545K), KIT (798I; M541L), and RUNX1 (L56S)." (PMID 34714554, 2022). "The results support the existence of an EGF-mediated downstream ERK1/2-RSK-rpS6 signalling pathway that bypasses EGFR in the presence of high OTR expression and compromised OTR signalling, which could be a cancer growth or survival adaptation." (PMID 35884900, 2022). "Additionally, EGFR promotes epithelial-mesenchymal transition (EMT) and contributes to cancer stemness maintenance." (PMID 36234645, 2022). "A small limitation of this study was the selection of the receptor (EGFR) because they are not specific to cancer, and they are also present in normal cells in minor quantities; hence, our system will also approach normal cells." (PMID 35160746, 2022).